CD4 (CD4 molecule)
Diseases named in the same sentence as CD4 in open-access papers (continued):
Sharing a sentence is not in itself a finding about the gene and the disease.
COVID-19 (continued). "Patients with COVID-19 and convalescent patients show that a T cell response is associated with a reduction in disease severity, suggesting that a specific T cell response (CD4 and CD8) against SARS-CoV-2 could be important for the control and resolution of the primary infection." (PMID 37107714, 2023). "MALAT1 has been shown to be downregulated in severe COVID-19 patients and upregulated in mild COVID-19 patients in CD4+ T cells." (PMID 36950105, 2023). "For instance, CD4+ counts are important in HIV monitoring, CD4+ and CD8+ counts have been associated with COVID-19 severity and progression and natural killer cells have been implicated in various autoimmune diseases." (PMID 37118842, 2023). "We analyzed the expression of different Notch receptors on CD4+ Tregs and Tconv cells in pediatric patients with mild or severe COVID-19 and in those with MIS-C." (PMID 36282598, 2023). "The most striking associations among host factors and the SARS-CoV-2 repertoire among the COVID-19+ cohort were related to BMI and nadir CD4." (PMID 36805331, 2023). "More specifically, a polarization towards an exhausted/senescent state of CD4+ and CD8+ T cells is described 3 months after the infection, and a perturbation in CD4+ Treg subsets is visible up to 6 months after COVID-19." (PMID 37764934, 2023). "For example, malignant cells were found in most human cancer datasets, whereas CD4+ T cells were frequently found in COVID-19 and bacterial pneumonia datasets." (PMID 36243976, 2023). "Severe clinical outcomes occurred commonly in PLWH with COVID-19, especially with low CD4+ T-cell counts and in older subjects." (PMID 37006309, 2023). "In hospitalized COVID-19 patients, an increase in the CD8 T cells, and in some studies also in the CD4 T cells, was strongly associated with a successful treatment." (PMID 36752852, 2023). "A high-dimensional single-cell analysis showed that CD4+ T cell depletion, T cell differentiation, plasma cell amplification, and the reduced antigen presentation capacity of innate immunity in COVID-19." (PMID 37495990, 2023). "Of the two mixed cell types we detected in COVID-19 data, cytotoxic CD4+ cells were increased in moderate and severe disease." (PMID 37730638, 2023). "In patients with high-risk COVID-19, MHC and antigen presentation-related genes are downregulated, impairing the activation of CD4+ and CD8+ T cells." (PMID 36941461, 2023). "A third COVID-19 mRNA vaccine dose significantly boosted spike-specific CD4+ and CD8+ T-cell frequencies to above 2-dose levels in older and younger adults." (PMID 38035132, 2023). "Comparison of the T/NK cell subsets of patients with COVID-19 and controls revealed relative expansion of CD4+ T cells with cytotoxic activity (CD4+ CTLs), CD8+ effector memory T cells (TEM), NK cells, and CD56brightCD16dim NK cells in patients with COVID-19." (PMID 37606044, 2023). "In a study aimed to understand the development of memory immune responses post COVID-19 infection, the authors measured the circulating SARS-CoV-2 specific memory B cells, CD8+ T cells and CD4+ T cells for 8 months from a cohort of 188 COVID-19 patients." (PMID 37091818, 2023). "Multiple studies show a stable specific SARS-CoV-2 CD4 + cellular immune response between 2 weeks and 6 months after second COVID-19 vaccination in healthy individuals and for CVID patients." (PMID 36932291, 2023). "Various studies discovered that HIV patients with low CD4 counts and compromised immune systems who are in the advanced stages of the illness (stages 3 or 4) exhibit less severe COVID-19 symptoms." (PMID 37288215, 2023). "Another study showed that while the total percentage of γδ T cells decreased in COVID-19 patients, the percentage of CD4+γδ T cells significantly increased." (PMID 36793739, 2023). "Second, we tested these MR-identified genes for colocalization with COVID-19 outcomes across all time points following stimulation of CD4 + T cells." (PMID 37640912, 2023).
COVID-19 (continued). "The most frequently detected CD4+ T-cell peptide specificities in COVID-19 patients were aa236–250 (37%) and aa246–260 (44%), whereas the peptide specificities aa686–700 (50%) and aa741–755 (36%), were the most frequently detected in seronegative controls." (PMID 37215095, 2023). "Ninety-two percent of COVID-19 cases had circulating CD4 T cells at one month from symptom onset, while 92% had these cells after six months; CD4 T cells have a half-life of 94 days." (PMID 37107714, 2023). "The findings that vaccination-elicited antibody and CMI responses correlate to baseline viral loads, TFH counts, and CD4/CD8 ratios have implications for predicting COVID-19 vaccine efficacy in PLWH." (PMID 36239345, 2023). "Two doses of the vaccine produced a TCR repertoire in the CD4+ subset capable of recognizing epitopes throughout the spike protein with comparable depth and breadth found in convalescent COVID-19 patients." (PMID 37388738, 2023). "In a study that assessed immune activation in COVID-19 patients at 3–12 months post-hospital admission, patients with severe disease exhibited persistent activation of CD4+ and CD8+ T-cells." (PMID 38203577, 2023). "Different subpopulations of CD4+ T cells, such as Th1, Th2, Th17 and regulatory T cells (Treg), have been found to accumulate in COVID-19 patients." (PMID 36793739, 2023). "The deeper analysis of CD4+ T cells compartment revealed a decrease in the frequency of Treg cells in COVID-19 patients." (PMID 37809093, 2023). "We found that PWH with CD4 counts of < 200 cells/mm3 were less likely to receive a COVID-19 booster compared with PWH with CD4 counts > 500 cells/mm3." (PMID 37996521, 2023). "In patients with severe corona virus disease 2019 (COVID-19), progressive lymphocytopenia and depletion of lymphocyte subsets were observed, and PD-1 expression on CD4+ and CD8+ T cells was significantly increased in patients with poor prognosis." (PMID 38193090, 2023). "Several studies have reported the T cell immune profile in COVID-19-positive individuals, where in particularly CD4+ and CD8+ T cells are observed to be reduced with disease progression." (PMID 37886355, 2023). "One study on 701 COVID-19 patients reported that the counts of CD4+ T cells (≤500) and CD8+ T cells were significantly associated with mortality." (PMID 37799722, 2023). "Subgroup analyses further validated our findings about the predictive value of CD4 T-cell counts for seroconversion due to COVID-19 vaccines in PLWH (OR range, 2.30 to 9.59)." (PMID 37112701, 2023). "While we saw multiple univariate associations with sex and nadir CD4 in the COVID-19– cohort, we observed an interesting pattern of higher SARS-CoV-2–specific antibodies that engage FcγRIIB among those with lower nadir CD4 in the COVID-19+ group." (PMID 36805331, 2023). "In early studies on COVID-19, impairment in function and increased expression of markers, which are hallmarks for activation and/or exhaustion of CD4+ and CD8+ T cells, were observed in patients." (PMID 36793739, 2023). "The effect of the first and second dose of the COVID-19 vaccine on the activity of CD4+ and CD8+ T-cells is of particular interest." (PMID 37515127, 2023). "Antibodies decline more rapidly following vaccination in naive individuals than those in individuals who have recovered from COVID-19, but they display the same frequencies of spike-specific B and CD4+ T cells at 8 months after vaccination." (PMID 36845156, 2023). "Of note, while CD4+ T cells from healthy donors mostly target the C terminal part of the S glycoprotein, CD4+ T cells from COVID-19 patients target almost equally both the N- and C-terminal parts of the SARS-CoV-2 S glycoprotein." (PMID 37153606, 2023). "COVID-19 mRNA vaccines induce the maturation of CD4+ and CD8+ T-lymphocytes, and more than 70% of vaccinated individuals have memory T-lymphocyte responses." (PMID 36814238, 2023).
COVID-19 (continued). "For instance, it has been shown that severe COVID-19 patients had significantly fewer Tregs (CD3+ CD4+ CD25hi CD127lo FoxP3+) in their PBMCs." (PMID 36992283, 2023). "In fact, patients with COVID-19 presented the upregulation of T cell markers, such as CD4, CCL21, CD48 and TNFRSF1B/TNFR2." (PMID 37047248, 2023). "PBMC subsets level of COVID-19 patients in poor and death groups is significantly lower, such as CD4+, CD3+, CD8+ lymphocyte." (PMID 38095633, 2023). "A similar trajectory analysis in the pulmonary CD4+ compartment revealed a strong polarization of helper cells to Th1/Th17 in COVID-19, also denoted by a dysfunctional phenotype (according to gene expression) in severe disease." (PMID 36875071, 2023). "And the sensitivity analysis indicated that the count of lymphocytes (<500), CD3+ T cells (<100), CD4+ T cells (<100), CD8+ T cells (<100), and B cells (<50), were risk factors for COVID-19 patients’ death." (PMID 37799722, 2023). "The adjusted VE for any COVID-19 vaccine for participants with a CD4 < or =350 was 16.4% (95% CI: 0–67.6)." (PMID 38005865, 2023). "Recent investigations examined the percentage of Tregs among CD4+ cells in patients who still have COVID-19 symptoms and contrasted these to seronegative controls and COVID-19 survivors." (PMID 36992283, 2023). "CXCL10 is critical for CD8+ and CD4+ T cell recruitment and has been demonstrated to correlate with the severity of COVID-19." (PMID 37112926, 2023). "This gap was filled by our other study showing that CD4 T cell count is positively correlated with seroconversion among COVID-19 vaccinated patients with HIV85." (PMID 37336939, 2023). "Although cells produce COVID-19 antibodies, CD4+T cells can differentiate into a series of helper cells and effector cell types, which can guide B cells, help CD8+ T cells, and recruit innate cells." (PMID 37559719, 2023). "In mild COVID-19 patients, the effector CD4+ or CD8+ T cells will proliferate and form a defense mechanism during the acute phase." (PMID 36839596, 2023). "In conjunction with these results, patients treated with demeclocycline exhibited an increase in CD4+ T cell counts, which correlated with a decrease in IL-6 levels following treatment, suggesting the attenuation of COVID-19." (PMID 37612352, 2023). "We found that most of the enriched pathways in COVID-19-positive individuals were derived from activated CD4+ T cells, followed by CD8+ TCM, and CD8+ TEM cells." (PMID 37886355, 2023). "Vaccination against SARS-CoV-2 induces both CD4+ and CD8+ T cell responses and permits protection from severe COVID-19, including infection with the currently circulating variants of concern." (PMID 36839516, 2023). "In our study, we observed a significant reduction in CD4 expression in monocytes of severe or critical COVID-19 patients as well." (PMID 37488118, 2023). "Several studies have confirmed the impaired immune system caused by COVID-19 and a significant reduction of lymphocytes, especially a decrease of B cells, natural killer (NK) cells, CD3+ T cells, CD4+ T cells and CD8+ T cells in peripheral blood examination." (PMID 37799722, 2023). "The results indicate that PLWH, especially those with CD4 cell count < 200/μL were still relatively vulnerable even after two doses of inactivated COVID-19 vaccination." (PMID 36670363, 2023). "Infection of SARS-CoV-2 can promote the activation of B cells during the acute phase, then mature B cells will present the viral antigen to CD4+ T cells and consequently induce rapid antibody clonal expansion and diversification in patients with COVID-19." (PMID 37138704, 2023). "ML models were trained as binary classification tasks to predict mild, moderate, or severe COVID-19 TCR repertoires from healthy donor repertoires for either CD4 or CD8 ISB-S datasets." (PMID 36670287, 2023).
COVID-19 (continued). "The majority of SARS-CoV-2-specific CD4+ T cells from COVID-19 patients show a clear IFN-γ, tumor necrosis factor (TNF) and IL-2 protein signature characteristic of canonical Th1 cells." (PMID 36776863, 2023). "The COVID-19– participants with lower nadir CD4 tend to have antibody profiles that reflect a mix of activating and inhibitory responses to control chronic viral infections like EBV or CMV or from prior resolved infections." (PMID 36805331, 2023). "The abundance of CD8+ T cells, CD4+ memory resting T cells, follicular helper T cells, regulatory T cells, and monocytes was lower in the COVID-19 group than in the control group." (PMID 38384322, 2023). "In our study, we comprehensively evaluated the potential risk factors for seroconversion due to the COVID-19 vaccine in PLWH, including age, gender, CD4 T-cell counts, HIV viral load, comorbidities, days after complete days, and vaccine type." (PMID 37112701, 2023). "To support this presumption, when correlation analysis was preformed, we found strong positive correlation between percentage of CD4+IL-10+ cells and CD4+FoxP3+ cells in peripheral blood of COVID-19 patients in IV stage." (PMID 37057213, 2023). "COVID-19-enriched B. contaminans was negatively associated with the levels of lymphocytes, CD3+ T cells and CD4+ T cells." (PMID 37205106, 2023). "Expansion of CD4+ CTLs, DN B cells, and their contacts has been reported in T and B cell-activated diseases, including IgG4-related disease and COVID-19." (PMID 38077321, 2023). "Several studies detected a significant reduction in total lymphocytes count and in CD3+ and CD4+CD8+ T-cell subsets, both at the early stages and in severe forms of COVID-19-associated disease in deceased hospitalized patients compared to survivors." (PMID 36836679, 2023). "It was shown that the expression of Th17 cell-associated genes (RORC, IL17A, IL17F, and CCR6) was downmodulated in peripheral blood CD4+ T cells in COVID-19 patients." (PMID 37626620, 2023). "CD57+ CD4+ T cells are normally rare in the blood, although increased proportions have been reported in the context of infections, including COVID-19." (PMID 37161048, 2023). "In concordance, we found cell cycle regulation, lymphocyte differentiation, and proliferation enriched in the activated CD4+ T cells, possibly contributing to their activation in the COVID-19 positive individuals." (PMID 37886355, 2023). "Although the memory CD8+ T cell response after COVID-19 has declined over time and is generally lower than the memory CD4+ T cell response, the proportion of AIM+ CD8+ T cells in our Conv18mVx1 group was particularly deficient in our study." (PMID 35508998, 2022). "A recent study reported that PBMCs from severe COVID-19 patients show less CD4+ and CD8+ T cell activation and IFN-gamma production than PBMCs from mild cases in response to in vitro stimulation with M, N, and S viral proteins." (PMID 35860236, 2022). "Previous studies have shown that both convalescent COVID-19 patients and individuals vaccinated with any of the different COVID-19 vaccine platforms develop long-term immunity mediated by CD4+ and CD8+ specific T cells." (PMID 35746545, 2022). "Our results show an imbalance in the CD4+ T cell compartment during pediatric COVID-19 and suggest the involvement of extracellular ATP in its induction." (PMID 35663467, 2022). "The mRNA-based vaccines of COVID-19 induce maturation of CD4+ and CD8+ T lymphocyte and the vaccinated individuals tend to possess memory-based T-lymphocyte responses." (PMID 36298504, 2022). "Due to the significant prevalence of lymphopenia in COVID-19 patients and its strong correlation with disease severity, current research suggests that lymphocyte count, particularly CD4+ levels, can be employed as a predictive biomarker for disease severity." (PMID 36267156, 2022).
COVID-19 (continued). "Patients who suffered COVID-19 showed lower total blood lymphocyte compared to healthy individuals, including a significant decrease in counts of CD4+ T cells, CD8+ T cells, NK cells and NKT cells." (PMID 34975340, 2022). "CD4+ T cells specific to COVID-19 were rapidly induced in patients with acute COVID-19 and resulted in accelerated viral clearance." (PMID 35955740, 2022). "100% of COVID-19 convalescent participants displayed a detectable SARS-CoV-2-specific CD4 T-cell response." (PMID 34140294, 2022). "COVID-19 can damage CD4 T-cell functions and promote excessive activation and, possibly, subsequent exhaustion of CD8 T cells in severe cases." (PMID 36365007, 2022). "A study suggested that COVID-19 patient with pneumonia produced more in vitro IL-17, which boosted the inflammation response and activated neutrophils in vitro CD4+ and CD8+ T cells produced more of IL-17 in patients with pneumonia." (PMID 36034704, 2022). "Circulating SARS-CoV-2-specific CD8+ and CD4+ T cells can be identified in blood samples collected 20 to 35 days after onset of symptoms in 70% and 100% of COVID-19 convalescent patients, respectively." (PMID 35911696, 2022). "Recent studies have demonstrated that the presence of pre-existing cross-reactive CD4+ and CD8+ T cells is associated with reduction in the COVID-19 severity, supporting a protective role for T cells against disease." (PMID 35273178, 2022). "This is supported by the results of several recent studies carried out showing that in COVID-19 patients the CD4:CD8 ratio is in the normal range in spite of low CD4+ and CD8+ T cells." (PMID 35898494, 2022). "Patients defined as high based on number of inflammatory monocytes were older than low patients; patients defined as high based on amount of circulating CD4+CD45RO+ T-cells received more frequently heparin for their COVID-19." (PMID 35508575, 2022). "A similarly biased response of CD4+ Th cells was also recently observed in the peripheral blood of humans following AdHu5-COVID-19 vaccination." (PMID 34990408, 2022). "In some instances, COVID-19 disease severity has been attributed to poor SARS-CoV-2-specific CD4+ T cell polyfunctionality potential, reduced proliferation capacity, and enhanced HLA-DR expression." (PMID 35880744, 2022). "To address this question, we analyzed the SARS-CoV-2 spike glycoprotein-specific CD4+ T cell receptor repertoire before and after vaccination in 10 COVID-19 convalescent patients and 4 SARS-CoV-2 naïve healthy donor vaccine recipients." (PMID 35533495, 2022). "In a previous study from our group, we identified definite cutoff values for T-lymphocyte subset absolute counts (CD3+, CD3+CD4+, and CD3+C8+) assessed at ward admission and associated with an increased risk of in-hospital mortality for COVID-19 patients." (PMID 36359306, 2022). "In summary, these data demonstrated that in older adults, COVID-19 mRNA vaccination elicited a lower frequency of Spike-specific CD4+ and CD8+ T cells producing cytokines involved in T cell differentiation and proliferation." (PMID 37118289, 2022). "Of note, we saw an impressive reduction especially in CD4+CD25+FoxP3+ regulatory T cells (Tregs) in moderate/severe COVID-19 patients." (PMID 35265078, 2022). "Data indicate enhancement of CD4+ and CD8+ T-cytotoxic profiles in severe COVID-19 patients, whereas CD4+ T cells are less activated than CD8+ T cells." (PMID 36359755, 2022). "We first considered AIM+ CD4+ T cell reactivity within the cohort of 89 acute COVID-19 donors, as a function of mild, moderate, or severe disease states." (PMID 35806161, 2022). "Concerning the activated CD8+ T cell population expressing CD38 and HLA-DR, the levels were elevated compared to healthy controls and were sustained for more than 6 weeks, whereas the CD4+ T cells decreased over time within the COVID-19 patients." (PMID 36003367, 2022).